TSHZ2 (teashirt zinc finger homeobox 2)
Description:
Probable transcriptional regulator involved in developmental processes. May act as a transcriptional repressor (Potential).
Synonyms: OVC10-2; C20orf17; TSH2; ZNF218; ZABC2
Tractability: PROTAC: UniProt records ubiquitination sites on it; ubiquitination databases record sites on it.
Gene: Protein-coding gene on chromosome 20 (52,972,358 to 53,495,330, forward strand). Ensembl gene ENSG00000182463.
Subcellular location: Nucleus
Subcellular location (Human Protein Atlas): Golgi apparatus; Nucleoplasm
Gene Ontology:
Molecular function: protein binding; DNA binding; DNA-binding transcription factor activity, RNA polymerase II-specific
Biological process: regulation of transcription by RNA polymerase II; regulation of gene expression
Cellular component: chromatin; nucleus
Genetic constraint (gnomAD): Loss-of-function variants: 21 observed, 74.49 expected, observed/expected ratio (o/e) 0.28, 90% interval 0.2 to 0.41. The upper end of that interval is the gene's LOEUF score, 0.41, which puts it in group 1 of 6, group 1 being the genes least tolerant of losing a copy. Missense variants: 1,244 observed, 1,336.2 expected, observed/expected ratio (o/e) 0.93, 90% interval 0.89 to 0.98. Synonymous variants: 540 observed, 530.69 expected, observed/expected ratio (o/e) 1.02, 90% interval 0.95 to 1.09.
Homologues: Orthologues: chimpanzee TSHZ2 (99% identical), macaque TSHZ2 (97% identical), guinea pig TSHZ2 (93% identical), rabbit TSHZ2 (92% identical), dog TSHZ2 (92% identical), mouse Tshz2 (90% identical), rat Tshz2 (89% identical), tropical clawed frog tshz2 (71% identical), zebrafish tshz2 (58% identical), Drosophila melanogaster tio (16% identical), Drosophila melanogaster tsh (13% identical). Paralogues in human: TSHZ1 (53% identical), TSHZ3 (48% identical).
Diseases named in the same sentence as TSHZ2 in open-access papers:
TSHZ2 is named in the same sentence as 25 diseases in open-access papers, as found by Europe PMC text mining. Sharing a sentence is not in itself a finding about the gene and the disease. The quoted sentences say what the papers report.
breast carcinoma (8 papers, 2011 to 2021). "TSHZ2 (zinc-finger homeobox protein) was shown to be a transcriptional repressor that is downregulated in breast cancer cells and to exert negative regulation on Gli1 activity in normal and immortalized mammary gland duct epithelium." (PMID 32565808, 2020). "Of these genes, we focused on the role of the zinc-finger homeobox protein TSHZ2, which is down-regulated in breast cancer cells." (PMID 26744317, 2016). "Intriguingly, a previous report revealed that the promoter region of TSHZ2 is not methylated in breast cancer cell lines, leaving a question of how TSHZ2 is down-regulated in breast cancer cells for future investigation." (PMID 26744317, 2016). "In the present study, through the analysis and validation of publicly available microarray datasets, we identified TSHZ2, a zinc-finger homeobox gene, as one of three genes down-regulated in breast cancer cells compared with normal mammary glands." (PMID 26744317, 2016). "To this end, we established either TSHZ2 or a control LacZ-expressing cells from a human breast cancer cell line MCF-7 (MCF-7TSHZ2 and MCF-7LacZ, respectively) and searched for genes differentially expressed between MCF-7TSHZ2 and MCF-7LacZvia expression microarray analysis." (PMID 26744317, 2016). "For instance, we found that TSHZ2 over-expression in MCF-7 cells suppressed the expression of genes such as ADAM28, which was reported to impact on the breast cancer biology (see GSE64351 for the details)." (PMID 26744317, 2016). "The TSHZ2 gene promoter region was also unmethylated in all thecells and tissues examined with the exception of the MDA-MB-231 breast cancer cellline cells." (PMID 21423795, 2011). "Furthermore, being consistent with TSHZ2-mediated suppression of CXCR4 expression, we found that CXCL12-induced breast cancer cell migration was inhibited by the expression of TSHZ2 but neither LacZ nor TSHZ2del4." (PMID 26744317, 2016). "Comprehensive screening of genes down-regulated by TSHZ2 revealed that some, but not all, of these genes were up-regulated by GLI1 in a breast cancer cell line." (PMID 26744317, 2016).
prostate carcinoma (5 papers, 2016 to 2021). A carcinoma that arises from epithelial cells of the prostate gland. "Although TSHZ2 showed the highest mutation frequencies for colorectal and ovarian cancer cell lines only one out of the four MSI prostate cancer cell lines was positive for the TSHZ2 mutation." (PMID 27907910, 2017). "It was reported that circTshz2-2 increases adipogenesis-related gene expression, such as Pparγ and Fabp4, in obesity while other reports suggest that Tshz2 regulates tumorigenesis and epigenetic methylation in breast and prostate cancers, and is involved in the development of zebrafish." (PMID 34561612, 2021). "The down-regulation of TSHZ2 mRNA was also reported in breast and prostate cancer cell lines." (PMID 26744317, 2016).
anxiety disorder (1 paper, 2024). A category of psychiatric disorders which are characterized by anxious feelings or fear often accompanied by physical symptoms associated with anxiety. "For anxiety disorders, 18 SNPs are linked to genes including CAMKMT, ARPP19, SOCS5, TNS3, VWDE, TSHZ2, and others." (PMID 39165506, 2024). "Genes related to metal binding or metal ion binding (e.g., ATP9B, LMAN2L, TNS3, and TSHZ2) may play a role in the development of anxiety disorders." (PMID 39165506, 2024).
breast ductal carcinoma in situ (1 paper, 2025). "This study reveals that miR‐217 suppresses breast ductal carcinoma in situ (DCIS) by targeting DNMT1, reducing TSHZ2 promoter methylation and restoring TSHZ2 expression." (PMID 40909350, 2025).
diabetic neuropathy (1 paper, 2025). A chronic, pathological complication associated with diabetes mellitus, where nerve damages are incurred due to diabetic microvascular injury involving small blood vessels that supply these nerves, resulting in peripheral and/or autonomic nerve dysfunction. "In addition, further research is needed to explore the roles of specific biomolecules implicated in diabetic neuropathy development, such as SLC30A1, TRBJ2‐7, OLFM1, TCF7L2, MCF2L, CEP295NL, CEACAM22P, TSHZ2, and PDZD4." (PMID 40692573, 2025).
lung adenocarcinoma (1 paper, 2021). A carcinoma that arises from the lung and is characterized by the presence of malignant glandular epithelial cells. "Through our retrospective analysis of 226 cases of lung adenocarcinoma, a high expression of TSHZ2 was found to be significantly associated with the smoking index (p=0.008) and differentiation (p=0.005) but no other clinicopathological factors." (PMID 33850468, 2021). "We also retrospectively analyzed 226 lung adenocarcinoma patients after surgical resection using immunohistochemical staining, and the association of TSHZ2 expression with the patient survival was evaluated." (PMID 33850468, 2021). "Notably, the lung adenocarcinoma patients with a high TSHZ2 expression tended to have EGFR mutations less frequently and a preferable prognosis to those with a lower expression." (PMID 33850468, 2021). "We reported for the first time the TSHZ2 expression in lung adenocarcinoma cell lines and large-scale samples, finding that the overexpression of TSHZ2 markedly inhibited lung adenocarcinoma cell growth and migration and induced tumor cell apoptosis in vitro." (PMID 33850468, 2021). "We also found that that the TSHZ2 expression was negatively correlated with the EGFR expression in most lung adenocarcinoma cell lines." (PMID 33850468, 2021). "TSHZ2 expression in different lung adenocarcinoma cell lines and human tissue from patients was detected using Western blotting and immunohistochemical staining." (PMID 33850468, 2021). "Low expression of TSHZ2 was also observed in most lung adenocarcinoma tissues compared with adjacent tissues." (PMID 33850468, 2021). "In the present study, we investigated the aberrant expression of TSHZ2 in lung adenocarcinoma cells." (PMID 33850468, 2021). "Low expression of TSHZ2 was observed from the four patients in lung adenocarcinoma tissues compared with adjacent tissues." (PMID 33850468, 2021). "An elevated TSHZ2 expression was observed in 155(68.6%) tumor tissues samples of lung adenocarcinoma patients." (PMID 33850468, 2021). "The effect of TSHZ2 on cell proliferation, apoptosis and migration in lung adenocarcinoma cells was measured by CCK8, colony formation, flowcytometric analyses and wound-healing, respectively." (PMID 33850468, 2021). "We also analyzed the expression of TSHZ2 in 226 patients who had undergone complete surgical resection of lung adenocarcinoma by IHC staining." (PMID 33850468, 2021). "In summary, we provided functional evidence that a high TSHZ2 expression suppresses lung adenocarcinoma progression in vitro." (PMID 33850468, 2021). "We also examined the frequency and clinical significance of the TSHZ2 expression in a retrospective series of 226 patients who underwent lung adenocarcinoma resection and analyzed its impact on the patients' prognosis." (PMID 33850468, 2021). "A Western blot analysis indicated that TSHZ2 was expressed in various lung adenocarcinoma cell lines." (PMID 33850468, 2021). "The expression of TSHZ2 was first detected in lung adenocarcinoma cells and tissues." (PMID 33850468, 2021). "Taken together, these findings suggest that a high TSHZ2 expression may serve as a biomarker predicting a favorable prognosis and may be as a potential therapeutic target for patients suffering from lung adenocarcinoma." (PMID 33850468, 2021). "Furthermore, the elevated expression of TSHZ2 exerted as a tumor-inhibiting function, thereby increasing the lung adenocarcinoma survival." (PMID 33850468, 2021). "Our results indicated that TSHZ2 exerts a tumor-suppressive effect on the progression of lung adenocarcinoma and may serve as a candidate therapeutic target in lung adenocarcinoma treatment." (PMID 33850468, 2021). "Furthermore, the negative expression of TSHZ2 function as an independent risk factor for the overall survival of patients with lung adenocarcinoma." (PMID 33850468, 2021).
lung adenocarcinoma (continued). "Therefore, increasing the TSHZ2 expression in EGFR wild-type patients with lung adenocarcinoma might be a viable alternative treatment option." (PMID 33850468, 2021). "Furthermore, we found that the overexpression of TSHZ2 plasmids led to the dramatic inhibition of cell proliferation, colony formation ability, migration and apoptosis induction in PC9 lung adenocarcinoma cells." (PMID 33850468, 2021). "We previously found that TSHZ2 had a negative correlation with EGFR mutations, with EGFR wild-type patients with lung adenocarcinoma showing an expression rate of 32.4%." (PMID 33850468, 2021).
Stevens-Johnson syndrome (1 paper, 2019). Stevens-Johnson syndrome is a limited form of toxic epidermal necrolysis characterized by destruction and detachment of the skin epithelium and mucous membranes involving less than 10% of the body surface area. "Single nucleotide polymorphisms (SNPs) in TSHZ2 are known to be involved in Stevens-Johnson syndrome/toxic epidermal necrolysis with severe ocular complications (SJS/TEN with SOCs) in the Japanese population." (PMID 31584970, 2019).
tumor (9 papers, 2011 to 2026). "rs12625311 demonstrated a stronger association in the combined study and is located in intron 1 of TSHZ2, which encodes a transcriptional repressor that suppresses the transcriptional activity of genes involved in tumor development and growth." (PMID 31584970, 2019). "Subsequently, TSHZ2 expression was measured in tumor and adjacent normal tissues from 40 DCIS patients using RT‐qPCR and Western blot." (PMID 40909350, 2025). "MSP and ChIP assays were conducted to assess the impact of DNMT1 on the methylation of the TSHZ2 promoter in tumor tissues." (PMID 40909350, 2025). "Last, we leveraged the scRNA-seq data from XYZeq to visualize how individual MSCs expressed Tshz2 and Csmd1, two genes of divergent function that are spatially variable with respect to the tumor in the spleen." (PMID 33883145, 2021). "The RNA expression of TSHZ2 in tumor was significantly lower than normal tissue and the overall survival of patients with the higher TSHZ2 expression was lower (Fig. ​4)." (PMID 33850468, 2021). "RT‐qPCR and Western blot analyses showed that miR‐217 and TSHZ2 expressions were significantly increased in the tumor tissues of the Lv‐miR‐217 + oe‐NC group compared to the Lv‐NC + oe‐NC group, whereas DNMT1, SHH, and GLI1 expression were significantly decreased." (PMID 40909350, 2025). "However, we found that spleen/tumor MSCs expressed lower levels of Csmd1 but higher levels of Tshz2 in closer proximity to the tumor." (PMID 33883145, 2021). "However, most studies thus far have focused on TSHZ3 25, with only sporadic reports available concerning TSHZ1 and TSHZ2 in non-neoplastic diseases." (PMID 33850468, 2021). "TSHZ2 and FBXO47 have been implicated in the regulation of the cell cycle by controlling key molecules involved in this process, and their alteration could contribute to tumor progression." (PMID 40136626, 2025). "TSHZ2 inhibits the Hedgehog‐GLI signaling pathway, thereby limiting tumor proliferation, migration, and invasion." (PMID 40909350, 2025). "TSHZ2 and TSHZ3 genes turned out to be the most interesting candidates fornovel tumor suppressor genes." (PMID 21423795, 2011). "In our previous studies 18, we performed a microarray expression analysis using a combination of tumor tissues and cell lines based on recurrence or no-recurrence cases, and detected the abnormal expression of TSHZ2 from microarray profiles." (PMID 33850468, 2021). "Conversely, some genes (VSIG4, MFAP5, THY1, TSHZ2) showed little to no expression in tumor cells." (PMID 40954493, 2025). "In our previous studies 18, we performed a microarray expression analysis using a combination of tumor tissues and cell lines based on recurrence or no-recurrence cases; we found that TSHZ2 was up-regulated more than four-fold in one patient with high recurrence and metastasis." (PMID 33850468, 2021).
cancer (7 papers, 2011 to 2025). A tumor composed of atypical neoplastic, often pleomorphic cells that invade other tissues. "We found that the significantly activated regulons were involved in T cell biology (RORC, TCF7, NFATC1, and LEF1) or disease pathogenesis (IKZF2 for CD30+ TMF and BATF3 for cALCL) or reported cancer biology (POUZAF1 and TSHZ2)." (PMID 37790936, 2023). "However, unlike AMOTL1 and SDPR, the role of TSHZ2 down-regulation in cancer cells has not been fully elucidated." (PMID 26744317, 2016). "Therefore, we anticipated that the TSHZ2 and TSHZ3 promotersmight be hypermethylated in the non-expressor cancer cell line cells whereas in theexpressors they would be hypomethylated, as it has been demonstrated with othertumor suppressor genes." (PMID 21423795, 2011).
adenocarcinoma (1 paper, 2021). A common cancer characterized by the presence of malignant glandular cells. "Of note, the TSHZ2 expression was negatively correlated with the EGFR expression in most adenocarcinoma cells except for H1573 adenocarcinoma cells." (PMID 33850468, 2021). "Due to the differences in the TSHZ2 expression among adenocarcinoma cell lines, we subsequently transfected pDsRed-monomer-C1-TSHZ2 or siRNA-TSHZ2 into PC9 or A549 cells, respectively, and verified the results by Western blotting." (PMID 33850468, 2021).
TSHZ2 also shares sentences with these, for which no sentence is quoted: asthma (1 paper); clear cell renal cell carcinoma (1); colon cancer (1); entropion (1); gastric cancer (1); glioma (1); idiopathic pulmonary fibrosis (1); invasive ductal carcinoma (1); nasopharyngeal carcinoma (1); Obesity (1); ovarian carcinoma (1); pancreatic cancer (1); sarcoidosis (1); serous neoplasm (1); toxic epidermal necrolysis (1).